S100A9 (S100 calcium binding protein A9)
Diseases named in the same sentence as S100A9 in open-access papers (continued):
Sharing a sentence is not in itself a finding about the gene and the disease.
cystic fibrosis (7 papers, 2013 to 2023). Autosomal recessive disorder caused by pathogenic variants in the CFTR gene (cystic fibrosis transmembrane conductance regulator), which encodes a chloride and bicarbonate channel expressed in epithelial cells, and follow the diagnosis criteria. "Another study comparing acute respiratory distress syndrome (ARDS), cystic fibrosis, and COPD suggests that S100A8 and S100A9 are linked to chronic inflammation while S100A12 is linked to acute inflammation." (PMID 26464846, 2013). "HMGB1 like IL-1α is found in CF sputa, whereas S100A9 is a part of Calprotectin, a complex described as the Cystic Fibrosis protein in 1973." (PMID 26793709, 2015). "A number of studies have identified PTMs on the S100A8 and S100A9 subunits detected in specimens from humans including saliva, bronchial lavage fluid (BALF), sputum from cystic fibrosis patients, serum, plasma, nasal mucus, pimple pus, and kidney stones." (PMID 36826733, 2023).
depression (7 papers, 2021 to 2026). "Macrophage/microglia inflammation mediated by S100A9 is considered a pivotal pathogenic in depression after AMI and a major pathway for the treatment of PCF, suggesting that PCF is a promising therapeutic candidate for psycho-cardiology disease." (PMID 35814253, 2022). "Treatment with an S100A9 inhibitor reverses these changes, ameliorates cardiac and neurological pathology, and alleviates depression-like behaviour." (PMID 41301929, 2025). "Since S100A8 and S100A9 are involved in inflammation, which is related to depression, we selected them for validation by qRT‒PCR on individual samples from each participant, as opposed to proteomic analysis performed from a pool." (PMID 38049858, 2023). "Our results identify S100A9 as a promoter of macrophage/microglia inflammation, with a central role in depressive disorder induced by AMI." (PMID 35814253, 2022). "In this study, S100A9 was not only upregulated in the depression group but also increased in cancer cell lines with NE/COR treatment as well as in tumor-bearing mice with chronic stress, which was consistent with previous researches." (PMID 34650925, 2021). "Indeed, the effects of short-term S100A9 blockade closely recapitulate the consequences of reduced inflammation on cardiac function and depression." (PMID 35814253, 2022). "Thus, S100A9-mediated macrophage/microglial inflammation is pivotal in post-MI depression." (PMID 41301929, 2025). "Additionally, the relative expression of S100A9 was positively correlated with HAMD score of the depression samples, which may suggest a positive correlation between depression and cancer." (PMID 34650925, 2021). "For instance, the oncogene S100A9 was upregulated while the tumor suppressor genes HDC, AKAP12, SFRP5, and ALOX15 were downregulated in depression groups." (PMID 34650925, 2021). "The effects of S100A9 protein were attenuated by TLR4 inhibitor TAK-242, indicating that the dysfunction of S100A9/TLR4 signaling in the hippocampus could generate neuroinflammation and depression-like behaviors." (PMID 35814253, 2022). "Moreover, has_circ_0014220, has_circ_0014221, and their host gene S100A9 enriched in the IL-17 signaling pathway, augmented levels of the inflammatory cytokines IL-6, TNF-α, and IFN-γ in depression patients as well as tumor-bearing mice with CUMS." (PMID 34650925, 2021).
endothelial dysfunction (7 papers, 2014 to 2025). In vascular diseases, endothelial dysfunction is a systemic pathological state of the endothelium (the inner lining of blood vessels) and can be broadly defined as an imbalance between vasodilating and vasoconstricting substances produced by (or acting on) the endothelium. "Next, to further investigate the mechanisms underlying S100A9‐mediated endothelial dysfunction, we extracted endothelial cell populations from the scRNA‐seq dataset and conducted KEGG and GSEA pathway enrichment analyses." (PMID 40492585, 2025). "Consistent with these, our data showed that neutrophil‐derived S100A9 causes endothelial dysfunction through RAGE/PI3K/AKT pathways." (PMID 40492585, 2025). "S100A8, along with its heterodimer S100A9 have been widely associated with endothelial dysfunction and even considered as a biomarker for vascular diseases." (PMID 41286097, 2025). "The potential of S100-A9 to cause endothelial dysfunction and damage, as well as its overexpression during inflammatory states and its proinflammatory nature, may be of relevance to ME/CFS, a disease which is characterized by endothelial dysfunction and (dysregulated) inflammation." (PMID 39014464, 2024). "The results demonstrated that LY294002 also effectively ameliorated endothelial dysfunction induced by elevated S100A9 levels or neutrophil exposure." (PMID 40492585, 2025). "This study investigates the critical mechanisms underlying pulmonary hypertension progression, with a focus on the novel role of neutrophil‐derived S100A9 in endothelial dysfunction‐mediated pulmonary vascular remodeling." (PMID 40492585, 2025). "Data of our mechanistic experiments indicated that S100A9 mediated endothelial dysfunction by activating the RAGE/PI3K/AKT pathways, and its upregulation enhanced neutrophil adhesion to ECs, thereby promoting the progression of SuHx‐induced PH." (PMID 40492585, 2025). "We mainly elucidate the role of S100A9 in modulating inflammatory responses, amplifying tissue fibrosis, promoting vascular calcification, inducing endothelial dysfunction, and serving as a pivotal biomarker in inflammation‐associated CVD." (PMID 38504474, 2024). "By integrating human lung samples, multi‐omics analyses, animal models, and mechanistic in vitro studies, it is revealed that how neutrophil–endothelial interactions mediated through the S100A9‐RAGE‐PI3K‐AKT signaling pathway contribute to endothelial dysfunction and vascular remodeling in PH." (PMID 40492585, 2025). "Taken together, these data suggest that hypoxia enhances neutrophil‐endothelial cell interactions, leading to endothelial dysfunction and subsequent vascular remodeling, in which neutrophil‐derived S100A9 is likely involved though activating the RAGE‐PI3K‐AKT signaling pathways of ECs." (PMID 40492585, 2025). "In future studies, it is worth to further explore whether S100A9‐RAGE interacts with other signaling molecules using molecular intervention approaches, such as specific inhibitors or RAGE mutant constructs, to comprehensively elucidate the mechanisms underlying endothelial dysfunction." (PMID 40492585, 2025). "The collective findings highlight the pivotal role of the S100A9‐RAGE axis in CVD, as it exhibits pro‐inflammatory properties, induces endothelial dysfunction, and contributes to vascular calcification." (PMID 38504474, 2024). "In order to delineate the pathogenesis of MDS-related endothelial dysfunction suggested by the prognostic impact of EASIX, we measured serum levels of S100A9, IL1β and IL18 (both activated by caspase 1 from pro-cytokines)." (PMID 31712595, 2019). "However, PI3K/AKT may not be the only downstream signaling pathways involved in S100A9‐RAGE‐mediated endothelial dysfunction." (PMID 40492585, 2025).
Granuloma (7 papers, 2010 to 2023). A compact, organized collection of mature mononuclear phagocytes, which may be but is not necessarily accompanied by accessory features such as necrosis. "Our histological analysis of Mycobacterium bovis bacillus Calmette-Guerin-elicited granulomas in guinea pigs revealed that S100A9-expressing neutrophils bordered a unique M2 niche within the inner circle of concentrically multilayered granulomas." (PMID 36843852, 2023). "The granuloma model allows a direct quantitative comparison of the effect of S100A8/S100A9 tetramers on leukocyte recruitment triggered by a defined inflammatory stimulus within the same mouse." (PMID 36310133, 2022). "Because the M2 populations in guinea pig granulomas were abolished via treatment with celecoxib, a selective COX-2 inhibitor, we propose the S100A9/Cox-2 axis as a major pathway driving M2 niche formation in granulomas." (PMID 36843852, 2023). "Proteins mainly expressed in neutrophils, including S100A9, were accumulated in the caseous sub-compartments of TB and MAC-LD granulomas, suggesting that neutrophils infiltrate into the caseum, and exacerbate pathogenesis." (PMID 32010116, 2019). "To confirm the biological relevance of our data obtained in vitro, we used a cutaneous granuloma model, in which two biogel “plugs” were injected into the right (addition of lipopolysaccharide (LPS) plus S100A8/S100A9‐tetramer) and the left flank (addition of LPS only) of the mice." (PMID 36310133, 2022).
liver diseases (7 papers, 2014 to 2023). "Especially, serum S100A9 has been reported to be an interesting biomarker to monitor liver disease activity and to predict prognosis." (PMID 33462187, 2021). "Most recently, S100A9 has been identified as a critical player during multiple inflammatory liver diseases." (PMID 33462187, 2021). "To determine the impact of suppressed neutrophil recruitment in a more complex model of chronic liver disease we investigated the effects of S100A9 deletion on wound-repair and regeneration in an 8-week model of iterative CCl4-induced liver disease." (PMID 24333183, 2014). "Also, five proteins (HSP90B1, Protein S100-A9 [S100A9], MMP1, matrix metalloproteinase-9 [MMP9], and CSF3) in the IL17 signaling pathway are in phase III clinical trials for treating solid tumors and have the potential to treat liver diseases." (PMID 37209815, 2023). "Since the pathogenesis of liver diseases varies and the role of S100A9 in CHB have not been clarified, serum S100A9 levels from patients with CHB were measured in the present study, and their association with liver disease progression was also analyzed in detail." (PMID 29615081, 2018).
neuroblastoma (7 papers, 2012 to 2024). Neuroblastoma (NB) is the most common solid, extracranial childhood tumor. "To investigate whether ApoE isoforms can mitigate the cytotoxic effect of S100A9 aggregates on SH-SY5Y neuroblastoma cells, we used the MTT assay to measure cell viability." (PMID 38396791, 2024). "The S100A9 oligomers can be highly toxic if they are added to neuroblastoma cells." (PMID 30150640, 2018). "The cytotoxic properties of S100A9 amyloid aggregates produced at pH 4.5, 42 °C were examined by adding them to SH-SY5Y neuroblastoma cells." (PMID 30150640, 2018). "Since S100A9 is abundant within plaques and hippocampal tissues, we have assessed the cytotoxic damage which S100A9 amyloids can inflict on SH-SY5Y neuroblastoma cells." (PMID 24240735, 2014). "The effect of A1–40 on S100A9-induced cytotoxicity was investigated by pre-mixing S100A9 with various concentrations of A1–40 and incubating the samples with SH-SY5Y neuroblastoma cells for 1 d to 3 d." (PMID 22457725, 2012). "To investigate the effect of S100A9/A mixtures on cells of neural origin, we employed the WST-1 assay on the neuroblastoma SH-SY5Y cell line." (PMID 22457725, 2012). "The effect of S100A9, A1–40 and their aggregates on the viability of SH-SY5Y neuroblastoma cells was assessed using the WST-1 assay." (PMID 22457725, 2012). "Results from Calcein-AM staining support our findings from the MTT assay, specifically that the presence of lipidated ApoE isoforms did not change the toxic effect of S100A9 amyloids on neuroblastoma cells." (PMID 38396791, 2024). "We found that amyloids of S100A9 are cytotoxic to neuroblastoma cells, and the presence of either ApoE isoforms does not change the level of their cytotoxicity." (PMID 38396791, 2024).
pulmonary TB (7 papers, 2015 to 2024). "S100A9 has been recently predicted as an early diagnosis serum biomarker for pulmonary tuberculosis." (PMID 33156824, 2020). "We have also explored the specifically expressed serum proteins in TB patients by iTRAQ-2DLC-MS/MS, and found serum protein S100A9, SOD3, and MMP9 as new potential diagnostic biomarkers for pulmonary TB." (PMID 26198726, 2015). "In pulmonary TB, S100A9 contributes to neutrophil localization to granulomas, and both S100A8 and S100A9 are biomarkers of TB-related lung damage." (PMID 38861581, 2024). "Pulmonary TB is characterized by excessive inflammation, and we identified numerous inflammation-related proteins such as CRP, S100A8, and S100A9." (PMID 38512356, 2024).
renal fibrosis (7 papers, 2016 to 2025). A final common manifestation of a wide variety of chronic kidney diseases characterized by glomerulosclerosis and tubulointerstitial fibrosis. "Accordingly, S100a9-/− mice were found to be protected from UUO-induced renal fibrosis independently of leucocyte infiltration and inflammation and loss of S100A8/A9 shielded TEC from UUO-induced apoptosis and epithelial-mesenchymal transition." (PMID 41318746, 2025). "As two members of DAMP, S100A8 and S100A9, were reported to correlate with the onset and progression of bone marrow fibrosis and renal fibrosis." (PMID 36429008, 2022). "Adult S100A9-/- mice that were subjected to UUO were protected from renal fibrosis." (PMID 33117389, 2020). "In a S100A9-knockout mouse model, it was recently demonstrated that calprotectin played a crucial role in renal repair after ischaemia/reperfusion-induced kidney injury: S100A8/S100A9 inhibited M2-polarization of macrophages, thereby preventing the induction of renal fibrosis and damage after AKI." (PMID 26745147, 2016). "Targeting the S100A9 signaling with inhibitors could decrease inflammation, ameliorate kidney injury, improve renal function and improved long-term outcomes such as mortality reduction with decreased renal fibrosis." (PMID 38831322, 2024). "Adult S100A9-/- mice lacking the S100A8/A9 heterodimer that were subjected to UUO were protected from renal fibrosis." (PMID 33117389, 2020).
Splenomegaly (7 papers, 2020 to 2024). Abnormal increased size of the spleen. "In this regard, considering that tasquinimod has been shown to ameliorate bone marrow fibrosis and splenomegaly in JAKV617F mice, it would be worth evaluating whether this S100A9 inhibitor is also able to block monocyte hyperactivation and lower cytokine levels in this model." (PMID 39391311, 2024).
tuberculosis (7 papers, 2011 to 2021). A chronic, recurrent infection caused by the bacterium Mycobacterium tuberculosis. "Furthermore, S100A9 has been associated with tuberculosis development and can distinguish between different disease stages." (PMID 33567747, 2021). "S100A8 and S100A9 are small calcium-binding proteins that are expressed in tuberculosis patients and produced by activated neutrophils and monocytes." (PMID 21249199, 2011). "Disturbing the interaction between Rv1768 and S100A9 may be a potential therapeutic target for tuberculosis." (PMID 32457723, 2020).
chronic lymphocytic leukemia (6 papers, 2018 to 2022). "It was shown that the S100-A9 protein associated to exosomes represent a new pathway for NF-κβ activation in chronic lymphocytic leukemia cells." (PMID 30232403, 2018). "For example, chronic lymphocytic leukemia cells can activate each other during disease progression by transferring S100-A9 in EVs." (PMID 34395429, 2021). "The calcium-binding proteins S100A4, S100A8, and S100A9 are upregulated in chronic lymphocytic leukemia (CLL), while the S100A9 promotes NF-κB activity during disease progression." (PMID 35805957, 2022).
chronic rhinosinusitis (6 papers, 2020 to 2025). Chronic form of sinusitis. "Furthermore, increased S100a9 expression enhances matrix metalloproteinase production associated with cell proliferation in chronic rhinosinusitis." (PMID 40904186, 2025). "In respiratory pathologies, S100a9 promotes tissue remodeling of nasal epithelium in chronic rhinosinusitis with nasal polyps and modulates neuroinflammation through TLR4‐dependent pathways." (PMID 40904186, 2025). "Recently, we observed that S100A9 expression in chronic rhinosinusitis samples coincides with elevated plasma proteases, and S100A9 protein enhances MMP-7 and MMP-3 production and proliferation in the CCL-30 cell line." (PMID 34239729, 2021). "Richer and collaborators (2009) showed a decreased expression of S100A7, S100A8, S100A9, and SPINK5 genes in the airway mucosal epithelium of people with chronic rhinosinusitis, which they associated with a defective epithelial barrier in this condition." (PMID 32735560, 2020). "Finally, elevated levels of S100A9 protein are present in the nasal tissues of chronic rhinosinusitis (CRS) subjects." (PMID 34239729, 2021).
Cirrhosis (6 papers, 2009 to 2022). A chronic disorder of the liver in which liver tissue becomes scarred and is partially replaced by regenerative nodules and fibrotic tissue resulting in loss of liver function. "Our results have also shown S100A9 expression was significantly elevated in serum samples from cirrhosis patients compared to healthy donors, as well as a significant reduction in liver samples from CCl4- or BDL-treated TRPM8−/− mice." (PMID 35525986, 2022). "The activation of S100A9/NF-κB pathway in hepatitis C virus through DCLK1 induced cirrhosis, and DCLK1 overexpression was positively correlated with the expression of inflammatory genes." (PMID 36369000, 2022). "The activation of S100A9/NF-κB pathway in hepatitis C virus via DCLK1 induces cirrhosis, and DCLK1 overexpression is positively correlated with the expression of inflammatory genes." (PMID 36369000, 2022). "In contrast, epithelial and stromal cells, Kupffer cells, lymphocytes, and bile ducts showed expression of DCLK1 and S100A9 in cirrhosis." (PMID 25948779, 2015). "In the present study, the expression level of S100a10, S100a11, S100a6, S100a8 and S100a9 increased from cirrhosis to metastatic process when compared with the normal liver." (PMID 19638242, 2009). "Interestingly, increased DCLK1 expression correlated with S100A9 for the most cell-types in HCV-positive cirrhosis." (PMID 25948779, 2015). "The DCLK1 overexpression also correlates with increased levels of S100A9, c-Myc, and BRM levels in HCV/HBV-positive patients with cirrhosis and HCC." (PMID 25948779, 2015). "Because chronic inflammation associated with HCV infection is considered a major contributor to cirrhosis and the development of HCC, the transcriptome data provided legitimate basis to investigate the relationship between DCLK1 and S100A9 in the context of HCV infection." (PMID 25948779, 2015). "CHB patients with liver cirrhosis had higher S100A9 levels than CHB patients without cirrhosis." (PMID 29615081, 2018).